GZMA (granzyme A)
Diseases named in the same sentence as GZMA in open-access papers (continued):
Sharing a sentence is not in itself a finding about the gene and the disease.
infection (55 papers, 2009 to 2025). The state of being infected such as from the introduction of a foreign agent such as serum, vaccine, antigenic substance or organism. "To understand the influence of Tr1 cells on the systemic response to infection, we quantified the abundance of Tr1-associated molecules (granzyme A, IFNγ, IL-10, and LAG3) in plasma from the same blood samples used to study CD4+ T cells as a part of MUSICAL." (PMID 41000872, 2025). "Deficiency of gzmA and/or gzmB was associated with increased bacterial loads, especially in the case of gzmB at the primary site of infection at late stage sepsis." (PMID 28694562, 2017). "By contrast, viral loads in the livers of mice deficient in GzmB, either alone, or in combination with GzmA, were significantly higher than those observed in B6 mice at day 6 post-infection." (PMID 25502180, 2014). "For all infection experiments there was an upregulation of genes associated with cytotoxic cells, mainly granzyme A and B, perforin 1 and NKG2D." (PMID 24340121, 2013). "In rodent lung filarial infection, GzmB KO mice were more resistant to infection, whereas GzmA KO had increased worm burdens as compared to WT mice." (PMID 39137883, 2024). "In this study, we explored the relative contributions of GzmA and GzmB in providing protection against infection at the intestinal barrier." (PMID 39137883, 2024). "The GzmA levels were strongly down-regulated in koi at days 6 and 11 post-infection compared to the control to both CEV genogroups." (PMID 37465154, 2023). "We found that genes associated with antiviral immune responses to RNA viruses, including Mx, Gig2 and Viperin, were upregulated in the early phase of infection, followed by increased expression of CD8α and GZMa in the later stage." (PMID 36694262, 2023). "The down-regulation of GzmA in AS infected with genogroup I was observed on days 6 and 11 post-infection." (PMID 37465154, 2023). "Cytotoxic T cells are believed to be involved in virus clearance, and increased expression of CD8α and GZMa has been found to correlate with decreasing PRV-1 RNA levels in the later stage of infection." (PMID 36694262, 2023). "Infection of mice with a series of other RNA viruses also resulted in high serum GZMA levels early in infection, with NK cells identified as the likely source." (PMID 35119362, 2022). "We expected that the main cell source of GzmA in this model to be a component of the innate immune response since reduction of inflammation in GzmA-/- and GzmK-/- mice was observed within the first 24 h after infection." (PMID 34815792, 2021). "After overnight infection and treatment, higher frequencies of monocytes internalized GzmA compared to the protein levels adhered to the cell surface." (PMID 34413857, 2021). "GzmA is internalized within one hour at steady state, and is detected inside cells after infection and treatment." (PMID 34413857, 2021). "To further explore the timing and localization of GzmA in relation to mycobacteria, we performed a series of immunocytochemistry experiments during infection." (PMID 34413857, 2021). "Higher production of IL-17A, IFN-γ, IL-10, IP-10, GM-CSF, sFasL, Granzyme A, Granzyme B, Granulysin, and Perforin following infection positively correlated with HIV replication." (PMID 33214610, 2020). "GzmA levels peaked on day 2 post infection, reaching high levels (range ≈500–3,000 pg/ml) that were on average ≈7 fold higher in IRF3/7−/−mice than those seen in wild-type mice." (PMID 31993061, 2019). "Infection of mice deficient in type I interferon responses with CHIKV, Zika virus, or dengue virus resulted in high levels of circulating GzmA." (PMID 31993061, 2019). "In 9 out of 11 NHPs, plasma granzyme A levels increased relative to levels on day -1 (prior to infection) and usually peaked on day 4–8 post infection." (PMID 28207896, 2017).
infection (continued). "We also show that granzyme A is elevated in CHIKV-infected NHPs and in CHIKV patients, with circulating granzyme A levels in NHPs peaking day 4–8 post infection, which coincides with the peak of circulating IFNγ levels." (PMID 28207896, 2017). "Taken as a group, the peak granzyme A levels for the 9 animals were significantly elevated when compared with levels prior to infection (day -1)." (PMID 28207896, 2017). "On the other hand, pathways such as virus entry via the endocytic pathway, or granzyme A signaling, dendritic cell maturation and complement system pathways were found to be significantly modulated only during V3034 infection." (PMID 28446152, 2017). "In PLF, the percentage of NK cells expressing gzmA clearly decreased over time, while the MFI (i.e., the amount of gzmA expressed by gzmA+ NK cells) increased after infection." (PMID 28694562, 2017). "For this purpose, we infected WT mice intraperitoneally and analyzed the intracellular expression of gzmA and gzmB before and 6, 14, and 20 h after infection by flow cytometry." (PMID 28694562, 2017). "On the other hand, we observed a positive correlation between the expression of TNF-alpha and granzyme A only after infection with Y strain." (PMID 26147698, 2015). "We observed a positive correlation between the expression of TNF-alpha and the expression of Granzyme A only after the infection with Y strain." (PMID 26147698, 2015). "In vivo post challenge studies showed acute simultaneous expression of granzyme A and IFNγ in both type of infections in a tissue specific manner." (PMID 23409078, 2013). "Similar observations have been made for human CD8+ T cells, with both granzyme A and granzyme B expression decreasing from 60% 1 month after infection to 33% within 1 year after infection." (PMID 23230439, 2012). "Furthermore, we observed that the expression levels of granzyme A, granzyme B, perforin and granulysin in the indirect contact group were downregulated to varying degrees at 48 h post-infection." (PMID 40370406, 2025). "Elevated granzyme A expression and frequency of NK cells in severely ill patients at convalescence may reflect an ongoing infection or delayed recovery." (PMID 40766325, 2025). "Our analysis showed a decrease in the frequency of alveolar macrophages concomitant with an increase in that of infiltrating macrophages expressing antiviral genes as well as proliferating T cells, effector CD8 T cells, and T cells expressing granzyme A (GZMA) shortly after infection." (PMID 38887303, 2024). "In accordance with these results, our observation of increased production of GZMA in NK cells suggests that these cells could act rapidly during infection by the Type II (PTG) strain of T. gondii tachyzoites." (PMID 39031850, 2024). "But a higher number of CD8+ T cells among the total number of infiltrated T cells during the second week after infection in conjunction with upregulation of granzyme A and B transcripts — potentially also reflecting NK cell activation — suggest the cytotoxic nature of this response." (PMID 34676832, 2021). "WT, GzmA-/- and GzmK-/- mice showed a similar bacterial load in blood and spleen at both 18 and 42 h, time after which some animals had already begun to clear the infection." (PMID 34815792, 2021). "Detection of extracellular granzyme A in patients with infections or pro-inflammatory disease." (PMID 32508827, 2020). "Even if biased PAR-1 antagonists could be developed that did not inhibit platelet function, the very rapid early rise in GzmA levels post-infection likely also leaves an unrealistically narrow window between diagnosis and treatment initiation." (PMID 31993061, 2019). "What might be the physiological function (if any) of the rapid early post-infection rise in circulating GzmA?" (PMID 31993061, 2019). "However, we observed a higher expression of granzyme A by CD8+ T lymphocytes after infection with either strain compared to media control." (PMID 26147698, 2015).
infection (continued). "Viral loads in mice deficient for GzmA were equivalent to those of B6 mice in all organs tested, at both day 4 and 6, suggesting that, at least during the acute phase of infection, GzmA is not required for viral control." (PMID 25502180, 2014). "The inflammatory effect of GzmA does not seem to regulate bacterial control as GzmA deficient mice efficiently control infections like Mycobacterium tuberculosis, Listeria monocytogenes, Brucella microti, Klebsiella pneumoniae, Streptococcus pneumoniae, or Escherichia coli." (PMID 32655547, 2020). "Thus, the observed differences regarding granzyme A/granzyme B vs. CD107a/perforin abundances might be a result of complex ligand/receptor binding events induced early on during infection leading to discrete maturation of lytic granules in NK cells." (PMID 32038647, 2019). "It is not excluded that in addition to a caspase pathway of apoptosis also caspase-independent mechanism of immunological cells death can be used by PRRSV to debilitate immunological answer to infection, what could explain high up-regulation of GZMA gene expression observed in our analysis." (PMID 29882085, 2018). "Finally, immune factors prevent pathogenic infection in vertebrate gestational tissues, and our dataset identifies several candidate genes responsible for immune defence in the pregnant dunnart uterus (BPI, BPIFB1, GZMA and PRF1)." (PMID 29402916, 2018). "We found that ALV-J infection significantly increased the proportion of CD8+T cells in chickens and up-regulated the expression of cytotoxic genes like Granzyme A and antiviral genes like IFIT5 at 14 days post-infection (dpi)." (PMID 39696681, 2024). "During both CEV genogroups infections, the expression levels of most of the genes for T cell response, including CD4, CD8b1, and GzmA were down-regulated in AS and koi at all time points compared to day 0 control." (PMID 37465154, 2023). "The expression level of T cells is increased in patients with mild infection; among which, CD8+ T cells highly express cytotoxic molecules, such as granzyme A, which play an antiviral immune effect." (PMID 36212830, 2022). "There was evidence of mycobacterial control as early as 2 h post-infection as seen in and quantified as integrated density of BCG-GFP comparing untreated cells to GzmA-WT and GzmA-S195A treated cells." (PMID 34413857, 2021). "With the aim of evaluating whether gzmA and/or gzmB deficiency influences local bacterial outgrowth and subsequent dissemination, we determined bacterial loads in the PLF, blood, and liver and lung homogenates of WT, gzmA−/−, gzmB−/−, and gzmAxB−/− mice at predefined time points after infection." (PMID 28694562, 2017). "In blood, a higher percentage of NK cells expressed gzmA when compared to PLF NK cells, peaking at 14 h, while the MFI decreased after infection, especially at 20 h." (PMID 28694562, 2017). "Statistical analysis showed an overall strong correlation of Eomes expression with CD8α and granzyme A, as well as between granzyme A and IFN-γ expressions post infection." (PMID 23409078, 2013). "Granzyme A was expressed equally in CD4+ and CD8+ which is suggestive of the induction of CTL of both T cell subsets following bTb infection of cattle." (PMID 22359547, 2012). "We show that GzmA and GzmB are required to protect mice against oral, but not intravenous, infection with Salmonella enterica serovar Typhimurium, consistent with an intestine-specific role." (PMID 39137883, 2024). "We have shown previously that humans, nonhuman primates, and mice have elevated serum GZMA levels after infection with CHIKV." (PMID 35119362, 2022). "While fetal Vγ9Vδ2 T cells express granzyme A (GzmA) in the absence of infection, they do not express granzyme B (GzmB) or perforin, the main cytotoxic effector molecules that can efficiently kill infected cells." (PMID 34255746, 2021).
infection (continued). "At 16 h post-infection it appears that the smaller proportions of cells that would become infected after GzmA treatment had not internalized GzmA." (PMID 34413857, 2021). "In this infection model we have previously e.g. observed a prominent increase of CTL among leukocytes in the caecal mucosa and increased mRNA expression of genes for cytotoxic granule proteins such as perforin and granzyme A at 10 dpi." (PMID 34521339, 2021). "Remarkably, independent of the genotype infection-priming of NK cells resulted in an overall decreased abundance of virtually all detectable prototypic NK cell proteins with the exception of granzyme A and granzyme B that were even found at higher abundances." (PMID 32038647, 2019). "Herein we report that circulating GzmA is significantly elevated in humans and mice following infection with CHIKV, and show that it is also evaluated in mouse models of Zika virus (ZIKV) and dengue virus (DENV) infections." (PMID 31993061, 2019). "Our IPA-based canonical pathways prediction suggested that protein kinase A signaling, eumelanin biosynthesis, EIF2 signaling, and granzyme A signaling were simultaneously enriched in hBMECs upon infection with RS218 and PCN033, but not with HB101." (PMID 30340642, 2018). "Similar to TNF-alpha expression by CD4+ T cells after 72 hours, infection with either strain did not induce an increase expression of granzyme A." (PMID 26147698, 2015). "Our data showed a positive correlation between the expression of TNF-alpha and the expression of Granzyme A. Interestingly, this correlation was only observed after the infection with Y strain and not in media or infection with Col cl1.7." (PMID 26147698, 2015). "In addition to infection-induced inflammation, it has been reported that the anti-tumoral advantage observed in mice that do not express GzmB is lost when additionally GzmA is absent, that is, in GzmA/B dKO mice." (PMID 39137883, 2024). "Our data indicate that: 1) GzmA is internalized within mycobacteria-infected cells, suggesting that GzmA uptake could prevent infection and 2) that the active site is not required to inhibit intracellular replication." (PMID 34413857, 2021). "Once we had confirmed that the protection observed in GzmA-/- mice was not related with the control of infection, we analyzed if extracellular GzmA was detected in serum from septic animals and if the absence of GzmA attenuated the inflammatory response in mice." (PMID 34815792, 2021). "While these data do not explain the inverse pattern of granzyme A/granzyme B and perforin in infection-primed NK cells they provide evidence for fundamental differences regarding the regulation of transcription and translation for these cytotoxic mediators in NK cells." (PMID 32038647, 2019). "In addition, the level of persistent CHIKV RNA in feet on day 30 post infection was not increased in GzmA-/- mice when compared with C57BL/6 mice." (PMID 28207896, 2017). "We found that protein kinase A signaling, eumelanin biosynthesis, EIF2 signaling, and granzyme A signaling were simultaneously enriched in both RS218 and PCN033 infection groups, but not in the HB101 group." (PMID 30340642, 2018). "At 6 d post-infection splenic CD8+ cells were enriched and found to express gzmA, gzmB and gzmK mRNA but not gzmC in wt animals." (PMID 19838298, 2009).
infectious disease (2 papers, 2018 to 2021). A disorder directly resulting from the presence and activity of a microbial, viral, or parasitic agent in humans. "Granzyme A was identified as a cytotoxic T lymphocyte protease with multiple roles in infectious diseases." (PMID 30340642, 2018).
adenocarcinoma (1 paper, 2019). A common cancer characterized by the presence of malignant glandular cells. "To evaluate intertumoral immune cytolytic T-cell activity across the colon (COAD) and rectum (READ) adenocarcinoma samples, we initially calculated the transcript levels of GZMA and PRF1." (PMID 31429779, 2019).
kidney (1 paper, 2026). "Renal vasculitis correlated with kidney PD-1, CCL1, MIF, Granzyme A, IL-15, and BAFF." (PMID 42182101, 2026).
GZMA also shares sentences with these, for which no sentence is quoted: bacterial infection (4 papers); bladder cancer (3); multiple myeloma (3); pancreatic cancers (3); peritonitis (3); sarcoma (2); squamous cell carcinoma (2); acute graft versus host disease (1); acute kidney injury (1); allergic rhinitis (1); Allergy (1); Alzheimer disease (1); amyotrophic lateral sclerosis (1); androgenetic alopecia (1); astrocytomas (1); autism (1); breast invasive carcinoma (1); brucellosis (1); celiac disease (1); clear renal cell carcinoma (1); colitis (1); colorectal adenocarcinoma (1); cytomegalovirus infection (1); deficiencies (1); Encephalopathy (1); Familial hemophagocytic lymphohistiocytosis (1); fibrosis (1); gastric tumors (1); Granuloma (1); Graves disease (1).
A further 45 diseases each share a sentence with GZMA in 1 paper.